PARN (poly(A)-specific ribonuclease)
Description:
3'-exoribonuclease that has a preference for poly(A) tails of mRNAs, thereby efficiently degrading poly(A) tails. Exonucleolytic degradation of the poly(A) tail is often the first step in the decay of eukaryotic mRNAs and is also used to silence certain maternal mRNAs translationally during oocyte maturation and early embryonic development. Interacts with both the 3'-end poly(A) tail and the 5'-end cap structure during degradation, the interaction with the cap structure being required for an efficient degradation of poly(A) tails. Involved in nonsense-mediated mRNA decay, a critical process of selective degradation of mRNAs that contain premature stop codons. Also involved in degradation of inherently unstable mRNAs that contain AU-rich elements (AREs) in their 3'-UTR, possibly via its interaction with KHSRP. Probably mediates the removal of poly(A) tails of AREs mRNAs, which constitutes the first step of destabilization. Also able to recognize and trim poly(A) tails of microRNAs such as MIR21 and H/ACA box snoRNAs (small nucleolar RNAs) leading to microRNAs degradation or snoRNA increased stability.
Synonyms: DAN; DKCB6; PFBMFT4
Tractability: Small molecule: a structure with a bound ligand is known; it has a high-quality binding pocket. PROTAC: ubiquitination databases record sites on it; its protein half-life has been measured.
Target class: Enzyme; Hydrolase
Gene: Protein-coding gene on chromosome 16 (14,435,699 to 14,632,728, reverse strand). Ensembl gene ENSG00000140694.
Subcellular location: Nucleus; Cytoplasm; Nucleus, nucleolus
Subcellular location (Human Protein Atlas): Nuclear speckles
Pathways (Reactome):
Metabolism of RNA: Deadenylation of mRNA; KSRP (KHSRP) binds and destabilizes mRNA
Cellular responses to stimuli: ATF4 activates genes in response to endoplasmic reticulum stress
Gene Ontology:
Molecular function: cation binding; poly(A)-specific ribonuclease activity; protein binding; protein kinase binding; RNA binding; telomerase RNA binding; 3'-5'-RNA exonuclease activity; mRNA 3'-UTR binding; nuclease activity; metal ion binding; nucleic acid binding
Biological process: box H/ACA sno(s)RNA 3'-end processing; lncRNA processing; miRNA catabolic process; poly(A)-dependent snoRNA 3'-end processing; positive regulation of telomere maintenance via telomerase; regulation of telomerase RNA localization to Cajal body; telomerase RNA stabilization; female gamete generation; nuclear-transcribed mRNA poly(A) tail shortening; priRNA 3'-end processing; RNA modification; siRNA 3'-end processing; mRNA catabolic process; regulation of RNA stability; RNA catabolic process
Cellular component: nuclear speck; nucleolus; cytoplasm; cytosol; nucleus
Genetic constraint (gnomAD): Loss-of-function variants: 14 observed, 23.83 expected, observed/expected ratio (o/e) 0.59, 90% interval 0.39 to 0.92. The upper end of that interval is the gene's LOEUF score, 0.92, which puts it in group 3 of 6, group 1 being the genes least tolerant of losing a copy. Missense variants: 262 observed, 251.95 expected, observed/expected ratio (o/e) 1.04, 90% interval 0.94 to 1.15. Synonymous variants: 90 observed, 89.94 expected, observed/expected ratio (o/e) 1, 90% interval 0.84 to 1.19.
Gene-disease validity (ClinGen):
ClinGen rates the evidence that PARN causes each of these diseases.
pulmonary fibrosis and/or bone marrow failure, Telomere-related, 4 (semidominant): Definitive.
Homologues: Orthologues: chimpanzee PARN (99% identical), macaque PARN (99% identical), dog PARN (93% identical), pig PARN (93% identical), rabbit PARN (92% identical), guinea pig PARN (91% identical), mouse Parn (86% identical), rat Parn (86% identical), tropical clawed frog parn (74% identical), zebrafish parn (65% identical), Caenorhabditis elegans parn-1 (21% identical). Paralogues in human: PNLDC1 (24% identical), TOE1 (14% identical).
Diseases named in the same sentence as PARN in open-access papers:
PARN is named in the same sentence as 47 diseases in open-access papers, as found by Europe PMC text mining. Sharing a sentence is not in itself a finding about the gene and the disease. The quoted sentences say what the papers report.
dyskeratosis congenita (11 papers, 2017 to 2025). Dyskeratosis congenita (DC) is a rare ectodermal dysplasia that often presents with the classic triad of nail dysplasia, skin pigmentary changes, and oral leukoplakia associated with a high risk of bone marrow failure (BMF) and cancer. "A heterozygous VUS c.1514G>A (p.Arg505Gln) was detected in the PARN gene, which is associated with both autosomal dominant and autosomal recessive forms of dyskeratosis congenita (DC) spectrum disorders." (PMID 41459527, 2025). "Consistent with this idea, telomerase and Y RNAs are destabilized in the absence of PARN, which in the case of telomerase RNA likely contributes to symptoms of dyskeratosis congenita patients with genetic mutations in the PARN gene." (PMID 32499401, 2020). "Degradation of hTR is stimulated by the 3′ polyadenylation activity of the human TRAMP complex and antagonized by the poly(A)-binding protein PABPN1 and the deadenylase PARN, which is mutated in some cases of the premature aging disease dyskeratosis congenita (DKC)." (PMID 28202538, 2017). "The importance of the DEDD family deadenylases is underscored by genetic mutations in PARN and TOE1 genes leading to specific subtypes of human disorders dyskeratosis congenita and pontocerebellar hypoplasia (PCH), respectively." (PMID 32499401, 2020). "In addition to its involvement in cancer, mutations in the 3′-end processing enzymes, PARN and USB1, were implicated in the human diseases, dyskeratosis congenita (DC) and poikiloderma with neutropenia (PN), respectively." (PMID 40243428, 2025).
pulmonary fibrosis (10 papers, 2019 to 2025). Chronic progressive interstitial lung disorder characterized by the replacement of the lung tissue by connective tissue, leading to progressive dyspnea, respiratory failure, or right heart failure. "Rare telomere-maintenance gene pathogenic variants, such as TERT, TERC, RTEL1, and PARN, are principal causes of pulmonary fibrosis and familial pulmonary fibrosis and are associated with shorter telomeres, earlier disease onset, and poor outcomes." (PMID 41465275, 2025). "A careful follow‐up of parents carrying heterozygous PARN mutation is therefore needed to anticipate potential development of pulmonary fibrosis, progressive bone marrow failure, or other ailments associated with premature aging." (PMID 31273937, 2019). "Heterozygous PARN mutations have been associated with idiopathic pulmonary fibrosis and rheumatoid arthritis‐interstitial lung disease associated with short telomeres." (PMID 31273937, 2019). "Moreover, mutations in PARN are associated with DC and the familial form of idiopathic pulmonary fibrosis (IPF), an age-related disease featuring processive lung scarring." (PMID 37544646, 2023). "In contrast, loss-of-function mutations in PARN (PARN mutants) cause a severe form of DC called Hoyeraal-Hreidarsson syndrome, which causes abnormally short telomeres and congenital defects and idiopathic pulmonary fibrosis (IPF)." (PMID 37544646, 2023). "A subset of patients with pulmonary fibrosis (173/204) were previously evaluated for qualifying variants in telomere-related genes in TERT, RTEL1, or PARN." (PMID 37904125, 2023). "Indeed, heterozygous variants have been detected in familial forms of pulmonary fibrosis involving TERT (∼15%), RTEL1 (5–10%), PARN (∼5%), and TERC (∼3%)." (PMID 36833253, 2023).
idiopathic pulmonary fibrosis (5 papers, 2018 to 2024). Idiopathic pulmonary fibrosis (IPF) is a nonneoplastic pulmonary disease that is characterized by the formation of scar tissue within the lungs in the absence of any known cause. "Sequence variants in genes for surfactant proteins (SFTPC, SFTPA1, SFTPA2, ABCA3), polymorphisms in MUC5B or TOLLIP, and mutations in telomere genes (TERT, TERC, PARN, and RTEL1) are associated with an increased risk of idiopathic pulmonary fibrosis (IPF)." (PMID 36864460, 2023).
gastric cancer (4 papers, 2015 to 2024). A primary or metastatic malignant neoplasm involving the stomach. "In this study, PARN depletion was found to significantly inhibit the proliferation of gastric cancer cells and promote cell death." (PMID 38689093, 2024). "Taken together with previous observations in leukemias and gastric cancer these results imply that PARN affects a distinct subset of mRNAs in SCC." (PMID 26541675, 2015). "In gastric cancer, Zhang and Yan have studied PARN expression in two cell lines of gastric cancer origin, MKN28 and AGS, as well as datasets from Oncomine." (PMID 26541675, 2015). "A study on the impact of PARN in genome-wide expression analysis in other types of cancer, such as gastric cancer, would be greatly informative on possible commonly regulated factors/pathways by the enzyme." (PMID 26541675, 2015). "The reduced expression of transcripts may imply that these are not direct targets of PARN, and could be attributed to the compensatory activity of another deadenylase for the modulation of p21 steady-state levels upon PARN silencing in gastric cancer cells." (PMID 26541675, 2015). "Poly(A)-specific ribonuclease (PARN), which removes adenosine residues from the poly(A) tails after catalyzing mRNA deadenylation, was upregulated in gastric cancer, acute leukemia, and small cell lung carcinoma." (PMID 35892886, 2022).
acute leukemia (3 papers, 2015 to 2022). A clonal (malignant) hematopoietic disorder with an acute onset, affecting the bone marrow and the peripheral blood. "The phosphorylation of PARN has been observed in cells with serum starvation, DNA damage, and pathological conditions, such as acute leukemia." (PMID 31936572, 2020). "Recent work from our group showed that the levels of expression of several deadenylases -including PARN- are altered in acute leukemias." (PMID 26541675, 2015). "In acute leukemias, PARN expression is increased and its phosphorylation status is altered suggesting a potential use as biomarker." (PMID 26541675, 2015). "Recent work has shown that the expression of several deadenylases, including PARN and CNOT7, is altered in acute leukemias, and PARN may represent a promising biomarker and drug target." (PMID 26541675, 2015).
interstitial lung disease (3 papers, 2019 to 2023). A diverse group of lung diseases that affect the lung parenchyma.
lung carcinoma (3 papers, 2015 to 2026). "Herein, we show that PARN affects the expression of a subset of miRNAs in NCI-H520 cells of lung cancer origin, including miR-29a and miR-1207, which are also predicted to target PARN mRNA." (PMID 41825960, 2026). "Gene expression analysis upon PARN and NOC silencing in lung cancer cells revealed gene expression deregulation that was functionally enriched for gene ontologies related to cell adhesion, cell junction, muscle contraction and metabolism." (PMID 26541675, 2015).
rheumatoid arthritis (3 papers, 2019 to 2025). A chronic, systemic autoimmune disorder characterized by inflammation in the synovial membranes and articular surfaces. "Using whole-exome sequencing, it was demonstrated that TERT, RTEL1, and PARN mutations occur in patients with rheumatoid arthritis-associated ILD at a 3-fold higher odds ratio than they do in a control population." (PMID 40095034, 2025).
neuroblastoma (2 papers, 2012 to 2015). Neuroblastoma (NB) is the most common solid, extracranial childhood tumor. "Among the transcripts that are downregulated upon PARN silencing is C4orf6 (Chromosome 4 Open Reading Frame 6, Expressed In Neuroblastoma), an uncharacterized protein which is associated in neuroblastoma." (PMID 26541675, 2015). "The Cdk5r1 mRNA (stabilized 1.42-fold by PARN KD) encodes p35, an activator of the CDK5 kinase required for cell migration in neuroblastoma cells and for myogenic differentiation." (PMID 22956911, 2012).
pontocerebellar hypoplasia type 7 (2 papers, 2023 to 2024). "Functions of these enzymes are central to human health, with TOE1 mutations associated with Pontocerebellar Hypoplasia Type 7 (PCH7), PARN mutations with Dyskeratosis Congenita and other human disorders, PNLDC1 mutations with azoospermia, and USB1 mutations with Poikiloderma with neutropenia." (PMID 38194449, 2024).
squamous cell lung carcinoma (2 papers, 2015 to 2022). A carcinoma arising from squamous bronchial epithelial cells. "Trascriptomic analysis of Poly(A) deadenylase expression in squamous cell lung carcinoma referred only PARN and Nocturnin(NOC) type of Poly(A) deadenylase family, significantly over-expressed, with a significant prognostic value in specific subtypes." (PMID 35565367, 2022).
telomere syndrome (2 papers, 2019 to 2022). Accelerated aging syndromes often caused by inheritable gene mutations resulting in decreased telomere lengths. "TERC and TERT were initially the only genes tested in familial pulmonary fibrosis or telomere syndrome; other TRGs such as RTEL1 or PARN were later included in the NGS panel." (PMID 31796085, 2019).
acute lymphoblastic leukemia (1 paper, 2019). Leukemia with an acute onset, characterized by the presence of lymphoblasts in the bone marrow and the peripheral blood. "Meanwhile, changes in PARN phosphorylation status have been observed in samples from patients with acute lymphoblastic leukemia and acute myeloid leukemia." (PMID 31387300, 2019).
brain tumor (1 paper, 2025). "Targeting PARN in GSCs reduces tumor infiltration and prolongs survival in orthotopic brain tumor xenografts, suggesting that the STAT3-PARN regulatory network plays a pivotal role in tumor progression and represents a potential target for GBM therapeutics." (PMID 40277888, 2025).
breast carcinoma (1 paper, 2017). "By using normal and breast cancer cell lines that were mock-treated or that overexpressed PARN and/or PLD2, we defined the relationship between PARN and PLD2." (PMID 28011629, 2017). "In summary, we report for the first time the involvement of a phospholipase (PLD2) and PA in mediating PARN-induced eukaryotic mRNA decay and the crosstalk between the two enzymes that is deregulated in breast cancer cells." (PMID 28011629, 2017). "Surprisingly, in the MCF-7 breast cancer cells, both PARN and PLD2 protein co-overexpression augmented the expression of each of these proteins in parallel." (PMID 28011629, 2017). "Since phospholipase D (PLD2 isoform) gene expression is upregulated in breast cancer cells and PARN is downregulated, we examined whether a signaling connection existed between these two enzymes." (PMID 28011629, 2017). "Co-expression of both PARN and PLD2 mimicked this pattern in non-cancerous cells (COS-7 fibroblasts) but, surprisingly, not in breast cancer MCF-7 cells, where PARN switches from inhibition to activation of PLD2 gene and protein expression." (PMID 28011629, 2017). "We determined the endogenous gene expression of both PARN and PLD2 in COS-7 fibroblasts, used as a non-cancerous ‘normal’ cell line, as well as in the breast cancer cell line MCF-7." (PMID 28011629, 2017).
chronic lung allograft dysfunction (1 paper, 2021). Chronic lung allograft dysfunction encompasses a range of pathologies that cause a transplanted lung to not achieve or maintain normal function. "Moreover, it has been found that IPF with mutations in TERT, RTEL1, or PARN has a significantly higher risk of death and chronic lung allograft dysfunction compared to those in patients without these mutations." (PMID 34859008, 2021).
colon cancer (1 paper, 2020).
diabetes (1 paper, 2024). "It is suggested that PARN is a potential therapeutic target for diabetes." (PMID 39297407, 2024).
glioblastoma (1 paper, 2024). The most malignant astrocytic tumor (WHO grade IV). "A recent key study demonstrated that PARN activates EGFR-STAT3 signaling to exacerbate glioblastoma malignancy by degrading EGFR-targeting miR-719." (PMID 38689093, 2024).
Hoyeraal-Hreidarsson syndrome (1 paper, 2023). Hoyeraal-Hreidarsson syndrome (HHS) is a very rare X-linked recessive disorder considered to be a severe variant of dyskeratosis congenita characterized by intrauterine growth retardation, microcephaly, cerebellar hypoplasia, progressive combined immune deficiency and aplastic anemia. "Specifically, mutations in PARN were found in a severe form of DC known as Hoyeraal-Hreidarsson syndrome and IPF." (PMID 37544646, 2023).
invasive breast carcinoma (1 paper, 2017). A carcinoma that infiltrates the breast parenchyma. "Using the Finak Breast dataset from the ONCOMINE cancer microarray database, we determined that PARN was downregulated in invasive breast carcinoma compared to adjacent non-cancerous breast stroma, while gene expression of PLD2 was significantly upregulated in the same dataset." (PMID 28011629, 2017).
metastatic tumors (1 paper, 2015). "PARN overexpression correlated with younger patient age and CNOT6 overexpression with non-metastatic tumors." (PMID 26541675, 2015). "Further, PARN or NOC overexpression is observed in samples from patients with increased overall survival, while in samples derived from non-metastatic tumors the expression of CNOT6 was increased." (PMID 26541675, 2015). "We therefore examined the expression of these deadenylases using comparative quantification between SCC specimens and their matched non-pathological tissues, and we observed that PARN and CNOT6 overexpression correlated with younger patient age and non-metastatic tumors, respectively." (PMID 26541675, 2015).
Sepsis (1 paper, 2022). Sepsis is defined as life-threatening organ dysfunction caused by a dysregulated host response to infection. "Finally, we screened out two genes that were significantly associated with sepsis prognosis, NUDT4 and PARN." (PMID 36506322, 2022). "Therefore, the mechanism of PARN in sepsis deserves further discussion, especially whether PARN mediates immune cell apoptosis in sepsis deserves further attention." (PMID 36506322, 2022). "Finally, we screened the key genes in sepsis by WGCNA analysis, namely NUDT4 and PARN, and verified their expression patterns in sepsis in the datasets GSE131761 and GSE65682." (PMID 36506322, 2022). "In addition, we identified two potential therapeutic targets for sepsis, namely NUDT4 and PARN, both of which are closely related to the prognosis of sepsis patients." (PMID 36506322, 2022).
tauopathies (1 paper, 2019).